POLRMT (RNA polymerase mitochondrial)
Diseases named in the same sentence as POLRMT in open-access papers (continued):
Sharing a sentence is not in itself a finding about the gene and the disease.
cancer (continued). "Mitochondrial RNA polymerase (POLRMT) is often reported as a target protein for the treatment of malignant tumours, however snRNA-activating protein complex 5 (SNAPC5), also named SNAP19, has rarely been reported in tumours." (PMID 37441804, 2023). "As shown, relative expression of POLRMT in the malignant (cancer) cells is high among the cell clusters." (PMID 37816734, 2023). "Recently, inhibitors of the mitochondrial DNA-dependent RNA polymerase (POLRMT) were identified as potentially attractive new anti-cancer compounds." (PMID 37371693, 2023). "In both primary tumors and cancer cell lines, POLRMT overexpression promoted cell proliferation, migration, and invasion." (PMID 37371693, 2023). "Both ClpP agonists and POLRMT inhibitors have intriguing anti-cancer properties that will continue to be investigated as these compounds advance in clinical trials." (PMID 37371693, 2023). "Knockout of POLRMT also impaired multiple cancer-related processes such as cell proliferation, migration, invasion, and angiogenesis." (PMID 37371693, 2023). "Both ClpP agonists and POLRMT inhibitors induce major metabolic alterations in cancer cells, most prominently observed with the inhibition of OXPHOS." (PMID 37371693, 2023). "Comparatively, a potential drawback to POLRMT inhibition is that these inhibitors only primarily impact one process or cancer cell vulnerability (mitochondrial transcription)." (PMID 37371693, 2023). "It is not yet clear if these drugs reliably induce apoptosis in other cancer cells or if this is a common property of the anti-cancer response to ClpP agonists or POLRMT inhibitors." (PMID 37371693, 2023). "Alternatively, a lentiviral CRISPR/Cas9-POLRMT-KO construct was utilized to knockout POLRMT in phEC-1 cancer cells (“koPOLRMT” cells) (see “Methods”)." (PMID 36823110, 2023). "The importance of mtDNA transcription in tumor development is further underscored by a recent study where POLRMT levels were manipulated in human cancer cells." (PMID 34779571, 2022). "In this study, we used IMT1, a highly specific allosteric inhibitor of POLRMT, to study resistance mechanisms in treated cancer cells." (PMID 34779571, 2022). "Recent studies have supported POLRMT as a potential oncogenic gene and therapeutic target of human cancer." (PMID 35922422, 2022). "POLRMT and mitochondrial biogenesis levels are significantly elavated in breast cancer cells, important for cancer cell growth, and autophagy resistance." (PMID 34907167, 2021). "The rational for targeting POLRMT is that rapidly dividing cells such as cancer require high OXPHOS, whereas terminally differentiated cells such as heart and muscle show good tolerance to OXPHOS inhibition." (PMID 34976949, 2021). "It is foreseeable that POLRMT-targeted drugs for clinical cancer treatment will emerge in the near future to achieve precise eradication of cancer." (PMID 34976949, 2021). "The relative caspase-3 activity was significantly increased in POLRMT shRNA-expressing pOS-1 primary cancer cells." (PMID 34907167, 2021). "As shown, POLRMT mRNA expression in cancer tissues was significantly higher than that in the normal tissues." (PMID 34326320, 2021). "Recent studies have proposed a pivotal role of POLRMT in cancer growth and progression." (PMID 39227564, 2024). "Recent findings supported that POLRMT may serve as a pivotal oncogenic gene across various cancer types." (PMID 39227564, 2024). "Moreover, dysregulation of mitochondrial transcription factors, such as POLRMT, TFAM, TFB2M, and MTERFs, has been implicated in cancer development and progression." (PMID 38589371, 2024). "Both ClpP activation or POLRMT inhibition appears to increase glycolytic dependence in cancer cells (become more “Warburg-like”), although it is unclear why shifting cancer cells away from OXPHOS utilization would be therapeutically beneficial given that many cancers are already highly glycolytic." (PMID 37371693, 2023).
cancer (continued). "Ectopic overexpression of POLRMT should exert opposite activity and cancer-promoting functions." (PMID 36823110, 2023). "ClpP agonists and POLRMT inhibitors are promising new anti-cancer therapeutic strategies that may act through interrupting this important cellular function." (PMID 37371693, 2023). "A few recent studies have proposed the important cancer-promoting action by POLRMT." (PMID 36823110, 2023). "Importantly, both ClpP agonists and POLRMT inhibitors are reported to inhibit cancer cell proliferation with minimal effects on normal cells." (PMID 37371693, 2023). "Previous studies have revealed that POLRMT could be a novel and key oncogenic gene in several cancers." (PMID 36823110, 2023). "A remaining and important question is whether inhibition of POLRMT or activation of ClpP by small molecules results in the development of resistance in cancer cells." (PMID 37371693, 2023). "POLRMT protein upregulation in the cancer tissues was significant (P < 0.05 vs. “N” tissues)." (PMID 37816734, 2023). "Therefore, POLRMT shRNA/KO impaired mitochondrial functions and induced robust anti-cancer cell activity in phEC-1 cancer cells." (PMID 36823110, 2023). "Similarly, POLRMT inhibitors appear to be more effective at inhibiting cancer cell proliferation with minimal impact on normal cells." (PMID 37371693, 2023). "A survey of multiple studies indicates that ClpP agonists and POLRMT inhibitors may be differentially effective against different cancer types." (PMID 37371693, 2023). "Recent studies have proposed an essential role of POLRMT in the growth of different cancer cells." (PMID 37816734, 2023). "These POLRMT inhibitors potently suppressed cancer cell growth in mice." (PMID 34907167, 2021). "Recent studies have proposed POLRMT as a novel metabolic oncogene for human cancers." (PMID 34326320, 2021). "POLRMT inhibition by IMT1 induced robust cancer growth arrest." (PMID 34907167, 2021). "Furthermore, we discuss the rationale and strategies for designing new therapeutic molecules for MDR cancers by targeting POLRMT." (PMID 34976949, 2021). "Recent studies have proposed a cancer-promoting activity by POLRMT." (PMID 34907167, 2021). "Furthermore, analysis of TCGA datasets using the cBioPortal for Cancer Genomics indicated a correlation between MYC amplification and/or increased mRNA expression and increased POLRMT mRNA expression in cancer patient samples." (PMID 27590350, 2016). "While both ClpP agonists and POLRMT inhibitors show promising anti-cancer properties, there is the potential for the development of resistance, though this may be less likely with ClpP agonists because they effect many pathways including the TCA cycle, protein synthesis, and proline biosynthesis." (PMID 37371693, 2023). "Therefore, ectopic overexpression of POLRMT exerted pro-cancer activity in primary skin SCC cells." (PMID 35922422, 2022). "Therefore, POLRMT silencing induced profound anti-cancer activity in skin SCC cells." (PMID 35922422, 2022). "Recent studies have consistently affirmed the central role of POLRMT in mtDNA transcription, OXPHOS, energy production, and the proliferation of various cancer cell types." (PMID 38907279, 2024). "In breast cancer cells, elevated POLRMT expression and mitochondrial biogenesis (through OXPHOS) promoted cancer cell growth." (PMID 36823110, 2023). "The subgroup strongly expressing POLRMT had larger tumors, a greater incidence of metastasis, and a worse TNM stage, suggesting a clear role for POLRMT in cancer development." (PMID 37283308, 2023). "In addition to emphasizing the importance of mitochondrial transcription in mitochondrial function, elucidating the mechanism of action of ClpP agonists and POLRMT inhibitors could lead to broader discoveries about cancer and how to better treat this prolific disease." (PMID 37371693, 2023).
cancer (continued). "The cell viability was measured by CCK-8 assay and results showed that POLRMT silencing (by shPOLRMT-S1/S2) or KO (by CRISPR/Cas9 method) decreased viability (CCK-8 OD) in pCan1 primary cancer cells." (PMID 37816734, 2023). "Overexpressed POLRMT increased mtDNA transcription and mitochondrial OXPHOS, promoting cancer cell growth." (PMID 35922422, 2022). "Both POLRMT and HSP60 have been shown to be viable drug targets for cancer research, and provide potential further explanations for the anticancer properties of these compounds." (PMID 35929764, 2022). "POLRMT is essential for mtDNA transcription and OXPHOS, represents as a novel therapeutic target for human cancer." (PMID 34907167, 2021). "Although FLT3 wild-type and mutant cancers present with comparable sensitivity to venetoclax, the levels and activity of SUCLG1, SIRT5, and POLRMT and the potential synergy between venetoclax and SIRT5 inhibitors should be further examined in FL3-IDT AML cases." (PMID 38724759, 2024). "Both ClpP agonists and POLRMT inhibitors inhibit mitochondrial transcription, deplete mtDNA, impair OXPHOS, and are potentially disruptive to multiple aspects of cancer cell metabolism, making them distinct from other mitochondrial targeted approaches (i.e., metformin, CPI-613, etc.)." (PMID 37371693, 2023). "Herein we present a comparison of POLRMT inhibition and ClpP activation, both conceptually and experimentally, and evaluate the results of these treatments on mitochondrial transcription, inhibition of OXPHOS, and ultimately cancer cell growth." (PMID 37371693, 2023). "Then, a CDM signature with five cancer-dependent genes (MMS19, NOP14, POLRMT, SNAPC5 and TIGD1) and a prognostic nomogram were constructed, and they demonstrated robust predictive performance and a close relationship with clinical characteristics in different CC datasets." (PMID 37441804, 2023). "POLRMT inhibitors do not appear to be effective at inhibiting proliferation in all cancer cell lines in which they were tested." (PMID 37371693, 2023). "An outstanding question is why ClpP agonists and POLRMT inhibitors are effective inhibitors of cancer cell growth, but not normal cell growth." (PMID 37371693, 2023). "Tumor therapies targeting mitochondria have not been developed, and in particular, no drugs targeting POLRMT are currently available for clinical cancer treatment." (PMID 34976949, 2021). "Studies have shown that POLRMT could be an important metabolic oncogene, promoting OXPHOS progression and cancer cell growth." (PMID 34326320, 2021). "As described, two lentiviral shRNAs, targeting non-overlapping sequences of POLRMT, sh-POLRMT-1# and sh-POLRMT-2#, were separately transduced to pOS-1 primary cancer cells." (PMID 34907167, 2021). "Inhibition of POLRMT impairs mitochondrial transcription and OXPHOS protein synthesis, leading to dysfunction of the OXPHOS protein complex and cellular energy crisis, resulting in inhibition of a broad spectrum of cancer cells." (PMID 34976949, 2021). "Therefore, POLRMT inhibition or silencing shall impair mtDNA transcription and OXPHOS, resulting in significant cancer growth inhibition and cancer cell death." (PMID 34907167, 2021). "Therefore, POLRMT silencing failed to provoke apoptosis in non-cancerous skin cells, supporting a cancer cell specific effect." (PMID 35922422, 2022). "Therefore, treatments targeting POLRMT and TACO1 need to be evaluated in relation to whether they have a selective inhibitory effect on cancer cells, including BA in this study." (PMID 33923185, 2021). "The positive correlation of SUCLG1 expression with electron transport chain (ETC) components across numerous cancers suggests that SUCLG1 and SIRT5 influence POLRMT activity and mitochondrial biogenesis in non-AML cancers." (PMID 38724759, 2024).
cancer (continued). "This prediction suggests that cancer cells more reliant on OXPHOS may respond better to IMT1, whereas normal cells that are not as reliant on OXPHOS may be less affected by POLRMT inhibition." (PMID 37371693, 2023).
tumor (17 papers, 2015 to 2025). "POLRMT is a core component of the mitochondrial transcription machinery and is closely associated with tumor progression." (PMID 38589371, 2024). "However, the underlying molecular mechanisms by which POLRMT regulates tumor progression are not yet fully understood." (PMID 38589371, 2024). "Conversely, POLRMT shRNA or KO not only hindered mtDNA transcription, but also disrupted mitochondrial functions, causing significant ROS production, lipid peroxidation, depolarization of mitochondria and ATP depletion in skin SCC cells." (PMID 35922422, 2022). "Inhibition of POLRMT could disrupt mitochondrial metabolism at its source, causing an energy crisis and ultimately eradicating tumor cells." (PMID 34976949, 2021). "They found that MtPTAC effectively promotes the degradation of POLRMT mediated by ClpP in mitochondria and demonstrates its promising anti-tumor activity in vitro and in vivo." (PMID 38589371, 2024). "IMT1 inhibits the transcriptional activity of POLRMT, thereby suppressing the synthesis of mitochondrial OXPHOS proteins and causing an energy crisis in tumor cells, leading to inhibition of tumor proliferation." (PMID 38589371, 2024). "POLRMT, an RNA transcriptional polymerase indispensable for mitochondrial homeostasis, warrants the attention of tumor researchers." (PMID 37283308, 2023). "There were 39 cases of strong POLRMT expression in the tumor samples (n = 39/113, 34.5%), while there were only 11 cases of strong POLRMT expression in the adjacent normal tissues (n = 11/113, 9.7%)." (PMID 37283308, 2023). "POLRMT is over‐expressed in LUAD and is linked to WNT/beta‐catenin signaling; this potentially affects tumor infiltration, leading to unfavorable health outcomes for patients." (PMID 37283308, 2023). "Quantification results of all twenty patients’ POLRMT blotting data further confirmed that POLRMT protein is significantly elevated in the tumor tissues." (PMID 35922422, 2022). "Contrarily, further increasing POLRMT expression by a lentiviral construct enhanced mtDNA transcription and augmented skin SCC cell growth." (PMID 35922422, 2022). "Results showed that POLRMT mRNA transcripts in OS tumor tissues (n = 262) were significantly higher than those in normal bone tissues (n = 2)." (PMID 34907167, 2021). "Results showed that POLRMT mRNA upregulation in OS tumor tissues (P < 0.05 versus normal bone tissues)." (PMID 34907167, 2021). "POLRMT is overexpressed in most haematologic malignancies, and overexpressing the mitochondrial RNA polymerase increased tumour growth in a xenograft model of breast cancer, suggesting that POLRMT contributes functionally to tumour growth." (PMID 26484416, 2015). "Additionally, knockdown the POLRMT expression in vitro and in vivo also effectively inhibits tumor cell proliferation and migration." (PMID 38589371, 2024). "Dot plots generated from the dataset indicate that POLRMT is predominantly expressed in epithelial and endothelial cells, with a marked increase in expression observed in tumor samples, suggesting a potential role for POLRMT in tumorigenesis or tumor progression." (PMID 39227564, 2024). "Building upon the preceding findings, we postulated that the overexpression of POLRMT could potentially exert tumor-promoting effects." (PMID 39227564, 2024). "Studies have shown that increased expression of POLRMT is observed in lung cancer, osteosarcoma, squamous cell carcinoma, endometrial cancer, and acute myeloid leukemia, and it can promote tumor cell proliferation, invasion, and migration abilities." (PMID 38589371, 2024). "And DNA methylation of POLRMT was reduced in tumor tissues as compared to normal tissues." (PMID 37283308, 2023). "POLRMT was found to be significantly over‐expressed in the tumor samples." (PMID 37283308, 2023).
tumor (continued). "We also found that the methylation state of POLRMT was lower in tumor samples than in normal samples (p = 0.023); this was negatively co‐related to the POLRMT expression level in TCGA‐LUAD (Pearson rho = −0.15, p < 0.001) and CPTAC datasets (Pearson rho = −0.07, p = 0.514)." (PMID 37283308, 2023). "Furthermore, 2-C-methyladenosine, a POLRMT inhibitor, exerted potent anti-tumor response in AML cells." (PMID 34907167, 2021). "An adaptive response to this loss of respiratory equilibrium was observed through upregulation of mitochondrial electron transport chain transcription by POLRMT; ultimately, because of the loss of the MRP translational machinery, this adaptation failed, and the tumor cells succumbed to the drug." (PMID 28504693, 2017). "Furthermore, we dissected the relationship between POLRMT expression and tumor immune infiltration." (PMID 37283308, 2023). "Considering the uneven numbers of tumor and normal samples in TCGA‐LUAD, a paired analysis was performed that revealed elevated POLRMT expression." (PMID 37283308, 2023). "In patient-derived primary skin SCC cells or immortalized lines (A431 and SCC-9), POLRMT shRNA or KO potently suppressed mitochondrial DNA (mtDNA) transcription and suppressed cell viability, proliferation and migration." (PMID 35922422, 2022). "Similarly, inhibiting POLRMT with 2′-C-methyladenosine (2-CM), a potent inhibitor of HCV RNA-dependent RNA polymerase that also targets POLRMT, reduced mitochondrial gene expression in conjunction with AML tumor growth in a concentration-dependent manner." (PMID 36838782, 2023). "In A431 cells and SCC-9 cells as well as in primary skin SCC cells [derived from Patient-1# (“C1” cells) and Patient-2# (“C2” cells), the mRNA and protein expression of POLRMT was robustly higher than it in the primary human skin keratinocytes and fibroblasts]." (PMID 35922422, 2022). "The changes in OXPHOS system detected both in vitro and in vivo could explain the critical importance of POLRMT in rapidly dividing NSCLC cells, and why targeting POLRMT could have substantial anti-tumor effects against NSCLC cell both in vitro and in vivo." (PMID 34326320, 2021). "That is, POLRMT inhibitors target tumors with high oxygen metabolism in the MDR or relapsed population, while conventional drugs such as cisplatin and docetaxel, i.e., target tumor cells that are highly proliferative or glycolysis-dependent." (PMID 34976949, 2021). "One approach is to combine POLRMT inhibitors with other ABC transporter inhibitors in the clinic to completely kill tumor cells in a short period of time without giving them a window of time to adapt and develop tolerance." (PMID 34976949, 2021). "Moreover, the key mtDNA transcription factors POLRMT, TFAM, TFB1M and TFB2M were down-regulated in the GBM50 and GBM3 tumours." (PMID 30208958, 2018). "Moreover, recombinant over-expression of PGC1α/β, or other genes that promote mitochondrial biogenesis (MitoNEET/POLRMT), in MDA-MB-231 cells, was indeed sufficient to functionally increase tumor growth by up to ~3-fold." (PMID 26087310, 2015).